MIR5704 (microRNA 5704)
Synonyms: hsa-mir-5704
Gene: MicroRNA gene on chromosome 3 (131,985,855 to 131,985,931, reverse strand). Ensembl gene ENSG00000265859.
Homologues: Orthologues: chimpanzee MIR5704 (100% identical).